CD300C (CD300c molecule)
Synonyms: CLM-6; CMRF-35; IgSF16; CMRF35; CMRF35A; CMRF35A1; LIR; CMRF-35A; CMRF35-A1
Tractability: Antibody: UniProt places it where antibodies can reach, with high confidence; its Gene Ontology location is reachable by antibodies, with high confidence; UniProt predicts a signal peptide or a membrane-spanning region.
Gene: Protein-coding gene on chromosome 17 (74,534,362 to 74,546,133, reverse strand). Ensembl gene ENSG00000167850.
Subcellular location: Cell membrane
Subcellular location (Human Protein Atlas): Golgi apparatus; Mitochondria; Vesicles
Pathways (Reactome):
Immune System: Immunoregulatory interactions between a Lymphoid and a non-Lymphoid cell
Gene Ontology:
Molecular function: protein binding; transmembrane signaling receptor activity
Biological process: cellular defense response; regulation of innate immune response; signal transduction
Cellular component: plasma membrane
Genetic constraint (gnomAD): Loss-of-function variants: 11 observed, 17.45 expected, observed/expected ratio (o/e) 0.63, 90% interval 0.4 to 1.04. The upper end of that interval is the gene's LOEUF score, 1.04, which puts it in group 4 of 6, group 1 being the genes least tolerant of losing a copy. Missense variants: 273 observed, 286.23 expected, observed/expected ratio (o/e) 0.95, 90% interval 0.86 to 1.05. Synonymous variants: 116 observed, 115.34 expected, observed/expected ratio (o/e) 1.01, 90% interval 0.86 to 1.17.
Homologues: Orthologues: chimpanzee CD300C (96% identical), macaque CD300C (85% identical), pig CD300C (54% identical), mouse Cd300c (52% identical), rat Cd300c2l1 (50% identical), mouse Cd300c2 (50% identical), rat Igsf7l1 (49% identical), rat AABR07030796.1 (48% identical), rat AABR07030773.1 (47% identical), rat Cd300cl1 (47% identical), rat Cd300a (41% identical), rat Cd300cl1 (40% identical). Paralogues in human: CD300A (61% identical), CD300H (39% identical), CD300E (35% identical), CD300LD (31% identical), CD300LF (28% identical), CD300LB (26% identical), CD300LG (26% identical), FCMR (23% identical), TREML1 (21% identical), FCAMR (20% identical), TREM2 (20% identical), PIGR (19% identical), and 1 more.
Diseases named in the same sentence as CD300C in open-access papers:
CD300C is named in the same sentence as 15 diseases in open-access papers, as found by Europe PMC text mining. Sharing a sentence is not in itself a finding about the gene and the disease. The quoted sentences say what the papers report.
Allergy (3 papers, 2019 to 2021). An allergy is an immune response or reaction to substances that are usually not harmful. "In order to further assess the clinical relevance of those findings, we have studied the expression of CD300c on basophils from patients with two IgE-dependent allergies." (PMID 31641408, 2019). "Thus, an overexpression of CD300c was observed on basophils from cow’s milk-allergic children and also on basophils from dust mites- and grass pollen-allergic individuals, three types of IgE-dependent allergies." (PMID 32365988, 2020). "Based on our data, we propose that baseline expression levels of CD300c, together with CD63 expression, on human basophils could be helpful for the diagnosis of IgE-dependent allergies." (PMID 31641408, 2019). "We observed that surface CD300c expression levels are significantly higher in basophils from individuals with an IgE-dependent allergy (dust mites and grass pollen) than in those from non-allergic individuals." (PMID 31641408, 2019).
autoimmune disease (1 paper, 2018). A disorder resulting from loss of function or tissue destruction of an organ or multiple organs, arising from humoral or cellular immune responses of the individual to their own tissue constituents. "Therefore, CD300c protein has the potential to be used in the treatment of GVHD, autoimmune disease, and transplant rejection." (PMID 30498497, 2018). "Our results suggest that therapeutic interaction with the CD300c inhibitory pathway may represent a new strategy to modulate T cell-mediated immunity for the treatment of GVHD and autoimmune disease." (PMID 30498497, 2018).
COVID-19 (1 paper, 2021). A disease caused by infection with severe acute respiratory syndrome coronavirus 2. "Therefore, we decided to determine the expression of the inhibitory receptor CD300a and activating receptors CD300c and CD300e on monocytes from patients with COVID-19." (PMID 33777054, 2021).
glioma (1 paper, 2024). A benign or malignant brain and spinal cord tumor that arises from glial cells (astrocytes, oligodendrocytes, ependymal cells). "Especially, CD300C, CNRIP1 and MYO1F are the top three genes that engage in immune response in the glioma's microenvironment." (PMID 39448550, 2024).
graft-vs.-host disease (1 paper, 2018). "Administration of CD300c-Fc protein attenuates graft-vs.-host disease (GVHD) in mice." (PMID 30498497, 2018).
tumor (3 papers, 2021 to 2025). "Recent studies have highlighted the dual immunomodulatory roles of CD300 family members in tumor immunity, with CD300a acting as an inhibitory checkpoint and CD300c serving as an activating receptor that promotes pro-inflammatory responses in myeloid cells." (PMID 41378295, 2025). "Moreover, additional studies are warranted to clarify how CL7-mediated CD300c engagement triggers MAPK and NF-κB signaling in tumor-associated macrophages and how these pathways subsequently shape T cell activation." (PMID 41378295, 2025). "CD300c engagement activates pro-inflammatory signaling cascades in myeloid cells, potentially enhancing monocyte trafficking and M1-type differentiation upon tumor infiltration." (PMID 41378295, 2025). "The main finding of our research is that CL7, an anti-CD300c antibody, promotes M1 macrophage polarization in the TME while concurrently reducing Treg infiltration, resulting in significant tumor volume reduction." (PMID 41378295, 2025). "Previous studies have demonstrated that targeting CD300c with a monoclonal antibody activates MAPK and NF-κB pathways, promoting M1 macrophage polarization and suppressing tumor growth in preclinical models." (PMID 41378295, 2025). "Taken together, our findings demonstrate that CL7, a CD300c-targeting antibody, exerts potent antitumor effects in NSCLC by reshaping the tumor immune microenvironment." (PMID 41378295, 2025).
cancer (1 paper, 2023). A tumor composed of atypical neoplastic, often pleomorphic cells that invade other tissues. "We found that CD300LB, CD300C, and CD300LF were significantly hypomethylated in almost all cancer types as compared to normal samples." (PMID 35642341, 2023).
CD300C also shares sentences with these, for which no sentence is quoted: acute monocytic leukemia (1 paper); Alzheimer disease (1); autoimmune encephalitis (1); food allergy (1); infection (1); lung adenocarcinoma (1); non-small cell lung carcinoma (1); ovarian carcinoma (1).